SIX1 (SIX homeobox 1)
Diseases named in the same sentence as SIX1 in open-access papers (continued):
Sharing a sentence is not in itself a finding about the gene and the disease.
breast cancer (continued). "To determine whether Six1 levels are higher in the TIC population of cultured luminal breast cancer cell lines, thus enabling their use for mechanistic studies, we performed the functional tumorsphere assay to enrich for TICs in MCF7 and T47D luminal breast cancer cells." (PMID 22765220, 2012). "Finally, we demonstrate that Six1 expression correlates with phosphorylated ERK (pERK) levels in human breast cancers, suggesting that Six1 mediates its tumor promotional activities through activation of both TGF-β (previously shown) and MEK/ERK signaling in the human context." (PMID 22765220, 2012). "However, Six1 is re-expressed in breast cancers, suggesting that its re-instatement in the adult mammary gland may contribute to breast tumorigenesis via initiating a developmental process out of context." (PMID 20074369, 2010). "Interestingly, tumor formation occurs at a higher frequency in the animals that express low levels of Six1, indicating that Six1 may act in a dose-dependent manner to induce mammary tumors." (PMID 20074369, 2010). "Interestingly, overexpression of Six1 over long periods of time is sufficient to induce mammary tumors, suggesting that the appropriate levels of cofactors may be present for Six1 to properly activate transcription in a tumorigenic context." (PMID 20074369, 2010). "Sine oculis homeobox 1 (SIX1) is a transcription factor and is reported to be a GLUT1 regulator in breast cancer." (PMID 36230935, 2022). "We found that compared with normal breast tissue, the expression of SIX‐1, lncATB and ZEB1 was increased in breast cancer tissue, while the expression of miR‐200c‐3p was decreased." (PMID 32227618, 2020). "To date, the profiles of SIX1 and EYA1 have been independently identified as a prognostic biomarker in breast cancer." (PMID 31921695, 2019). "In agreement with our finding, knockdown of EYA2 antagonized the SIX1-induced TGF-β signaling, and partially restored epithelial properties with a decrease of the mesenchymal marker fibronectin in breast cancer MCF-7 cells." (PMID 30761270, 2019). "We found strong positive correlations between SIX1, SNAI1 or TWIST1 with GLI1 (a Hh pathway target) in numerous breast cancer data sets." (PMID 28604738, 2017). "Six1 is correlated with nuclear Smad3 and increases TGF-β signaling, promoting metastasis and relapse in breast cancer." (PMID 27916872, 2016). "Specifically, Six1 and EYA1 upregulated cyclin D; In contrast, DACH1 acted as an antagonist of cyclin D1 in breast cancer." (PMID 25322986, 2014). "Our results strongly suggest that Six1 increases TICs through activation of both TGF-β and MEK/ERK signaling in breast cancer cells." (PMID 22765220, 2012). "It is reported that knockdown Eya2 deletion in breast carcinoma cells inversed Six1 ability to facilitate TGF-β pathway, as well as to promote properties correlated with EMT and CSCs, proposing that Six1-dependentm Eya2 process to regulate a variety of pro-metastatic features." (PMID 38372877, 2024). "In this study on breast cancer, we also observed increased expression of p-STAT3 and C-MYC, suggesting that Six1's regulation of breast cancer stem cells may also involve the STAT3 signaling pathway." (PMID 38031089, 2023). "Furthermore, SIX1 overexpression enhances self-renewal capacity and promotes EMT in breast cancer cells, contributing to a stem-like phenotype." (PMID 38031089, 2023). "Indeed, our own group demonstrated that a developmental homeoprotein, SIX1, induces a CSC phenotype in luminal B breast cancer cells through induction of MAPK/ERK signaling." (PMID 32391382, 2020). "SIX1, SIX2, and SIX4 are activated in breast cancer patients." (PMID 27399099, 2016). "Sineoculis homeobox homolog (SIX) family proteins, including SIX1, SIX2, SIX3, SIX4, SIX5, and SIX6, have been implicated in the initiation and progression of breast cancer, but the role of each member in breast tumor is not fully understood." (PMID 27399099, 2016).
breast cancer (continued). "SIX1 and SIX6 could serve as an unfavorable factor for prognosis of luminal breast cancer patients, while SIX3 is capable of playing a protective role in prognosis of basal-like breast cancer patients." (PMID 27399099, 2016). "High SIX1 contributed to poor OS (HR: 1.64, 95% CI: 1.13–2.39; P = 0.705 and I2 = 0.0%) and RFS (HR: 1.43, 95% CI: 1.06–1.93; P = 0.112 and I2 = 38.4%) of luminal breast cancer patients." (PMID 27399099, 2016). "To investigate whether Six1-mediated downregulation of RPL26 is relevant to human cancer, we performed western blot analysis on seven breast cancer patient-derived xenografts (PDXs)." (PMID 26687066, 2015). "Finally, we examined the expression of Six1 and phosphorylated extracellular signal-regulated kinase (p-ERK) in human breast cancers." (PMID 22765220, 2012). "Indeed, we previously reported that Six1 and nuclear localization of the TGF-β effector Smad3 were significantly correlated in human breast cancer samples." (PMID 22765220, 2012). "Therefore, the interplay between SIX1, EMT, and CSCs must be considered in future investigations, particularly in the context of mechanisms governing the effects of SIX1 on breast cancer pathobiology, with the goal of identifying new therapeutic targets for breast cancer patients." (PMID 38031089, 2023). "In most adult tissue, SIX1 is not highly expressed; however, increased SIX1 expression has been documented in multiple cancers, including breast cancer 10, 11, ovarian cancer 12, Wilm's tumors 13, lung cancer 14, hepatocellular carcinoma 15, 16 and colorectal cancer." (PMID 32201523, 2020). "Besides, SIX1 promoted EMT, metastasis, and chemotherapy resistance in breast cancer cells." (PMID 32550045, 2020). "Via activation of TGF-β and MAPK signal, SIX1 enhanced the accumulation of cancer stem cells (CSCs) as well as induced epithelial-mesenchymal transition (EMT), and even switched the role of TGF-β/SMAD signal from tumor suppressors to oncogenic proteins in breast cancer." (PMID 31921695, 2019). "While expression of Six1 is low or absent in most adult tissues, it is re-expressed in a number of different human cancers including cervical, hepatocellular, ovarian, and breast cancer, as well as in alveolar rhabdomyosarcomas (RMS), and Wilms' tumors." (PMID 20074369, 2010). "However, we could not find any significant association between SIX1 mRNA expression and MFS of whole breast cancer population (HR: 1.08, 95% CI: 0.84–1.39; P = 0.244 and I2 = 22.4%)." (PMID 27399099, 2016). "Surprisingly, we also observed a similar trend in two other subtypes of breast cancer, namely HER2 positive and triple-negative breast cancer (TNBC), where patients with high SIX1 expression had a poorer prognosis compared to those with low expression." (PMID 38031089, 2023). "For example, high SIX1 mRNA level was significantly correlated with poor OS and RFS of breast cancer population, but not correlated with MFS." (PMID 27399099, 2016).
hepatocellular carcinoma (21 papers, 2006 to 2025). A malignant tumor that arises from hepatocytes. "Increased Six1 expression in macrophages promotes hepatocellular carcinoma growth and invasion by regulating MMP-9." (PMID 38509734, 2024). "For example, miR‐204‐5p inhibited the proliferation of hepatocellular carcinoma by directly regulating SIX1 and its downstream factors." (PMID 31373443, 2019). "It was reported that in multiple types of human cancer, such as breast, rhabdomyosarcomas, hepatocellular carcinomas, ovarian, and Wilms tumors, overexpression of Six1 was frequently identified." (PMID 26161040, 2015). "Inhibition of endogenous Six1 expression suppresses tumorigenesis and metastasis of hepatocellular carcinoma." (PMID 23527134, 2013). "Notwithstanding these significant findings of SIX1, the mechanisms of SIX1 regulation of hepatocellular cancer proliferation are still largely unknown." (PMID 29435409, 2018). "Thus, we demonstrated that miR‐204‐5p suppresses hepatocellular cancer proliferation by targeting the 3′UTR of the SIX1 homeobox gene." (PMID 29435409, 2018). "O-GlcNAcylation of sine oculis homeobox homolog 1 (SIX1) enhances its stability by inhibiting the ubiquitination degradation of SIX1, which promotes hepatocellular carcinoma proliferation." (PMID 40642069, 2025). "However, whether the role of SIX1 and the molecular mechanisms that regulate its activity are similar in hepatocellular carcinoma (HCC) still needs further investigation." (PMID 32863962, 2020). "Moreover, it has been shown that ROS-mediated mitochondrial fission leads to increased survival of hepatocellular carcinoma (HCC) cells, and that the downregulation of Six1 by miR-488 inhibits Drp1-mediated mitochondrial fission, resulting in the sensitization of ovarian cancer cells to cisplatin." (PMID 31947673, 2020).
BOR syndrome (16 papers, 2009 to 2025). "Downstream effectors of Six1 are good candidates to be associated with BO/BOR syndrome or non-syndromic forms of hearing loss." (PMID 40213817, 2025). "In particular, Six1-deficient mice show severe developmental defects in the ear and kidney, among other organs, which strongly resemble BOR syndrome symptoms." (PMID 37017267, 2023). "These are responsible for about 40% of clinical BOR syndrome, whereas approximately 4 and 5% of patients have pathogenic variants respectively in SIX1 gene and SIX5 gene." (PMID 36183088, 2022). "While CD is not strictly classified as a genetic kidney cystic disease, it has been associated with mutations including EYA1 and SIX1, which are linked to conditions like BOR syndrome, or other causes of congenital anomalies of the kidney and urinary tract (CAKUT)." (PMID 38254980, 2024). "Here, we have used Six1-deficient mice, an animal model of the BOR syndrome, to investigate whether dysfunction of senescence underpins the developmental defects associated with SIX1 deficiency." (PMID 37017267, 2023). "Genetic analysis reveals that mutations in EYA1, SIX1 and SIX5 cause BOR syndrome, an autosomal dominant developmental defect characterised by branchial and external ear malformations, hearing loss and renal anomalies." (PMID 38353121, 2024). "Approximately 40% of patients with BOR syndrome carry a pathogenic mutation in EYA1, whereas 9-10% have mutations in SIX1 or SIX5." (PMID 38353121, 2024). "In humans, mutations in SIX1/SIX2 and EYA1 are likely to affect downstream events, which contribute to various phenotypes of BOR syndrome." (PMID 38353121, 2024). "Biochemical assays verified the SIX1–DNA mechanism, demonstrating that BOR syndrome mutants in these residues significantly reduce DNA binding affinity." (PMID 37479820, 2023). "Mouse models of BOR syndrome, Eya1+/− and Six1+/− heterozygous mice, exhibit postnatal middle ear defects and pathology, which likely contribute to the deafness phenotypes." (PMID 36299576, 2022). "Mutations in SIX1 gene (MIM 601295), the human homolog of sine oculis, encoding a DNA binding protein that interacts with EYA1, have also been associated with BOR syndrome although less frequently than EYA1 mutations." (PMID 23506628, 2013). "In humans, mutations in EYA1 and its interacting partners SIX1 and SIX5 have been identified as causing BOR syndrome." (PMID 19389353, 2009). "BOR syndrome caused by EYA1, SIX1 and SIX5 mutations leads to kidney and urinary tract malformations and hearing impairment." (PMID 19389353, 2009). "Deletion of the Six1 or Eya1 genes in mice has confirmed the important role of these genes during the development of inner ear and other organs affected in BOR syndrome." (PMID 19389353, 2009). "In addition, variants in SIX homeobox 1 gene (SIX1 MIM#601205) and SIX homeobox 5 gene (SIX5 MIM#600963) were found to be related to BOR syndrome." (PMID 30548429, 2019). "Indeed, mutations in Six gene family members such as SIX1 and SIX5 also cause BOR syndrome while mutations in SIX2 have been reported in patients with renal hypodysplasia, a phenotype observed in patients with BOR syndrome." (PMID 24489909, 2014). "Mutations in EYA1, SIX1 and SIX5 genes have been associated with BOR syndrome." (PMID 23840632, 2013). "Interestingly, SIX1, SIX5, and EYA1 are associated with BOR syndrome." (PMID 30086703, 2018). "The presence of branchial cysts, cervical fistulae, external ear anomalies and mild renal pyelectasis suggested the clinical diagnosis of BOR syndrome and the analyses of EYA1, SIX1, and SIX5 genes were performed by next generation sequencing (NGS)." (PMID 36183088, 2022). "The phenotype of the Six1 null mouse is more severe than the phenotype in BOR patients and targeted Six1 heterozygote mice have a phenotype less severe than BOR syndrome." (PMID 19389353, 2009).
BOR syndrome (continued). "There are some reports of patients with atypical BOR syndrome, which does not satisfy the clinical criteria for typical BOR syndrome, despite carrying EYA1 or SIX1 mutations." (PMID 35046468, 2022).
Wilms tumor (15 papers, 2010 to 2025). An embryonal neoplasm characterized by the presence of epithelial, mesenchymal, and blastema components. "In doing so and when compared to other blastemal tumors, we identified upregulated expression of the gene encoding the non-canonical WNT ligand WNT5A in both chemotherapy-naïve and chemotherapy-treated blastemal Wilms tumors harboring the SIX1-Q177R mutation." (PMID 37815464, 2023). "The same Q177R mutation has been identified in SIX2 in Wilms tumors but occurs almost half as frequently as SIX1-Q177R." (PMID 37815464, 2023). "Overall, our findings have uncovered disrupted signaling networks linked to the regulatory behavior of SIX1/2-Q177R, providing additional clues to aid in our understanding of the complex underlying biology of Wilms tumors." (PMID 37815464, 2023). "The Genomic Regions Enrichment of Annotations Tool (GREAT) was used to identify potential target genes regulated by SIX1 and/or SIX1-Q177R in Wilms tumor by ChIP-seq peak-gene association (P<0.005)." (PMID 37815464, 2023). "The SIX1-Q177R mutation is almost exclusively heterozygous in Wilms tumors and, in the heterozygous context, both wild-type SIX1 and SIX1-Q177R alleles are expressed at similar levels." (PMID 37815464, 2023). "Most recently, two study groups showed that mutations in DGCR8, Drosha, together with mutations in SIX1/2, are associated with blastemal type Wilms tumors (WT)." (PMID 26308063, 2015). "Therefore, we aimed to conduct expanded and novel comparisons to interrogate SIX1 regulatory programs in Wilms tumor, particularly those associated with the SIX1-Q177R mutation." (PMID 37815464, 2023). "Considering that SIX1/2-Q177R is primarily heterozygous in Wilms tumors, the upregulation of some targets associated with this mutation might result from a synergistic interaction between wild-type and mutant alleles." (PMID 37815464, 2023). "The goal of this study was to expand upon previous reports and more clearly define the regulatory role of SIX1-Q177R in Wilms tumor by utilizing genomic data available from large-scale studies of these tumors in tandem with SIX1 ChIP-seq data from normal hFK." (PMID 37815464, 2023). "Ultimately, our studies are limited by the availability of Wilms tumor tissues – particularly blastemal predominant tissue and SIX1/2-Q177R mutant tumors – for thorough experimental validation." (PMID 37815464, 2023). "SIX1 ChIP-seq datasets from Wilms tumors revealed shared binding sites for SIX1/SIX1-Q177R within a promoter of WNT5A and at putative distal cis-regulatory elements (CREs)." (PMID 37815464, 2023). "To address the possibility of WNT5A regulation by SIX1, we turned to available SIX1 ChIP-seq data generated from wild-type SIX1 and SIX1-Q177R mutant Wilms tumors." (PMID 37815464, 2023). "Cluster 2 showed expression of the nephron progenitor markers SIX1, SIX2 and CITED1, as well as the stromal marker PAX3 that has previously been associated with myogenic Wilms' tumours." (PMID 30846463, 2019). "The pan-cancer study reported mutation in SIX1, TAL1, and ID4 were present in the Wilms Tumors, T-lineage acute lymphoblastic leukemias, and B-lineage acute lymphoblastic leukemias, respectively." (PMID 31681566, 2019). "Together with the mutations in SIX1/2, mutations of DGCR8 and Drosha are associated with Wilms tumor." (PMID 26308063, 2015). "Six1 expression is increased in cancers derived from tissues where it plays an important developmental role, including Wilms' tumors (derived from the kidney) and rhabdomyosarcoma (derived from the muscle)." (PMID 20074369, 2010). "Nonetheless, together with our finding of specific upregulation of WNT5A in tumors harboring the SIX1/2-Q177R mutation, this observation indicates that WNT5A may be a direct regulatory target of SIX1/SIX1-Q177R in Wilms tumor." (PMID 37815464, 2023).